PANX1 (pannexin 1)
Diseases named in the same sentence as PANX1 in open-access papers (continued):
Sharing a sentence is not in itself a finding about the gene and the disease.
Impaired glucose tolerance (1 paper, 2024). An abnormal resistance to glucose, i.e., a reduction in the ability to maintain glucose levels in the blood stream within normal limits following oral or intravenous administration of glucose. "Increased hepatic glucose production, impaired glucose tolerance, and elevated body and liver weight of PANX1-deficient mice were rescued by Ad-PANX1 injection (P < 0.05)." (PMID 38937853, 2024).
Infertility (1 paper, 2021). "On the other hand, some Panx1 mutations that lead to human oocyte development defects and infertility fit well with structural data." (PMID 34067798, 2021).
ischemic heart disease (1 paper, 2026). "Since this seminal study, Panx1 has been implicated in the pathophysiology of both ischemic and non-ischemic heart disease in cell and animal models." (PMID 41569301, 2026). "Research exploring Panx1 function in non-ischemic heart disease is currently in its infancy, mainly focusing on β-adrenergic agonist-induced cardiac hypertrophy, providing a novel field of research to explore in future studies." (PMID 41569301, 2026). "Like ischemic heart disease, evidence for Panx1 signaling in non-ischemic heart disease is male-dominant, with a more concerted effort required for translation to female models." (PMID 41569301, 2026).
joint diseases (1 paper, 2025). "Given that lysophospholipid and phospholipase concentrations are elevated in patients suffering from joint diseases, we hypothesized that synovial fluids from dogs with naturally occurring algogenic disease might trigger Panx1 activation." (PMID 40309905, 2025).
keratitis (1 paper, 2022). A corneal disease that is characterized by inflammation of the cornea. "In the pathological process of A. fumigatus keratitis, pyroptosis can also be regulated by upstream signals such as pannexin 1 and thymic stromal lymphopoietin." (PMID 35655803, 2022). "In human corneal epithelial cells and mice models of A. fumigatus keratitis, pannexin 1 channels contributed to IL-1β expressions via NLRP3/caspase-1 inflammasome." (PMID 35655803, 2022).
kidney (1 paper, 2021). "In contrast, HO-1 expression indicates an antiferroptotic effect, thereby inhibiting AKI Pannexin 1 (PANX1, an ATP-releasing pathway family protein), which has pro-apoptotic effects during kidney injury." (PMID 34944434, 2021).
Kidney Cyst (1 paper, 2026). Abnormal fluid filled sac within the kidney, either acquired or congenital. "Here, we demonstrate that the ATP-release channel Pannexin-1 is regulated by HIF-1α in kidney tubular cells, leading to its prominent localization at the apical membrane of kidney cysts in both human and murine ADPKD kidney tissue." (PMID 42117913, 2026).
liposarcoma (1 paper, 2023). A usually painless malignant tumor that arises from adipose tissue. "Dox also heightened Panx1 mRNA levels in primary human liposarcoma cell cultures." (PMID 37696858, 2023). "Notably, Panx1 transcription was tightly correlated with IL-6 gene expression in both primary human liposarcomas and clinical tumor tissues." (PMID 37696858, 2023).
lymphatic disorders (1 paper, 2021). "Whether we will be able to target Cxs for the treatment of lymphatic disorders will very much depend on the unraveling of the effects of the GJC2 and GJA1 gene mutations (and maybe in the future also GJA4 and Panx1 gene mutations) in relevant in vitro, ex vivo and in vivo models." (PMID 34072103, 2021).
lymphedema (1 paper, 2018). Excess fluid collection in tissues, causing swelling. "Indeed, neither the Panx1-deficient mice nor the only first patient with a PANX1 homozygous germline variant display obvious phenotypes such as lymphedema that would suggest alteration in lymphatic vasculature function." (PMID 29882918, 2018).
malignant glioma (1 paper, 2021). A grade III or grade IV glioma arising from the central nervous system. "However, in human malignant glioma cells, the levels of IL-6, IL-8, and glutamate were lower in Panx-1 siRNA transfected cells." (PMID 34475813, 2021).
metastatic disease (1 paper, 2023). "According to the logistic regression model, Panx-1 was an independent prognostic factor for regional metastatic disease in LSCC (p = 0.049, 95% CI: 0.563–0.980, OR: 0.76; regression coefficient −0.271)." (PMID 36833374, 2023). "Lower Panx1 and higher vimentin expression were found to be prognostic factors for regional metastatic disease." (PMID 36833374, 2023). "Indeed, lower Panx-1 expression was an independent prognostic factor for regional metastatic disease at diagnosis." (PMID 36833374, 2023).
muscular dystrophy (1 paper, 2014). Muscular dystrophy (MD) refers to a group of more than 30 genetic diseases characterized by progressive weakness and degeneration of the skeletal muscles that control movement. "Over-activity of Panx1, however, is thought to induce myocyte cell death; mutations in the dystrophin gene can up-regulate Panx1 expression, possibly contributing to the pathological apoptosis that leads to muscle wasting in those suffering from muscular dystrophy." (PMID 24600404, 2014).
Nephropathy (1 paper, 2024). A nonspecific term referring to disease or damage of the kidneys. "The discovery of peptide drugs for the treatment of CKD has attracted wide attention, with fibroin peptide notably ameliorating adriamycin-induced nephropathy by regulating lipid metabolism through the PANX1-PPARα/PANK1 pathway." (PMID 39290864, 2024).
non-small cell lung carcinoma (1 paper, 2024). A group of at least three distinct histological types of lung cancer, including non-small cell squamous cell carcinoma, adenocarcinoma, and large cell carcinoma. "Using GSEA analysis, PANX1 was found to be strongly associated with non-small cell lung cancer, leukocyte transendothelial migration, and cytokine signaling pathways." (PMID 38254708, 2024).
ocular hypertensive (1 paper, 2018). "Under ocular hypertension and ischemic conditions, however, high Panx1 activity permeated cell membranes and facilitated the selective loss of RGCs or stably transfected Neuro2A cells." (PMID 29643381, 2018).
opioid dependence (1 paper, 2017). "The second scenario involved chronic pain and opioid dependence in the spinal cord, where we predict ATP-induced endocytosis of Panx1 is impaired, possibly due to pathogenic changes in membrane lipids, leading to the observed upregulation in Panx1-mediated ATP release." (PMID 28848396, 2017).
ovarian carcinoma (1 paper, 2022). A malignant neoplasm originating from the surface ovarian epithelium. "Secondly, the survival analyses of patients with ovarian cancer clearly indicated that the expression levels of CALR, PDIA3, ANXA1, HMGB1, IFNAR1, and PANX1 had no significant influence on overall survival (OS) and disease-free survival (DFS)." (PMID 35991556, 2022). "Firstly, the expression analyses of patients with ovarian cancer showed that the expression levels of CALR and PDIA3 in ovarian cancer were significantly up-regulated in compared with normal control tissues, while the expression of PANX1, ANXA1, HMGB1, and IFNAR1 were nonsignificant." (PMID 35991556, 2022).
parasite infections (1 paper, 2022). "In parasite infections, T. cruzi or T. cruzi-virulence factors have been described to activate Panx1 hemichannels in cardiac cells, causing an outflow of ATP, and increasing the concentration of cytosolic Ca2+ through the activation of P2Y1 receptors, which is necessary for parasite invasion." (PMID 36699007, 2022).
periodontitis (1 paper, 2024). An acute or chronic inflammatory process that affects the tissues that surround and support the teeth. "The integration of GWAS with the expression quantitative trait locis of these genes from the peripheral blood genetically prioritized 6 candidate genes, including 2 risk genes (RAP2A, MCUR1) and 4 protective genes (WNK1, NFIX, FOS, PANX1) in periodontitis-related T2D." (PMID 38811930, 2024). "The integration of GWAS with the eQTLs of these genes from the peripheral blood prioritized 6 genes, including MCUR1, RAP2A, FOS, PANX1, NFIX and WNK1, in the pathogenesis of periodontitis-related T2D." (PMID 38811930, 2024). "MCUR1, RAP2A, FOS, PANX1, NFIX and WNK1 may play important roles in the pathogenesis of periodontitis-related T2D, shedding light on the development of potential drug targets." (PMID 38811930, 2024). "Furthermore, MCUR1, RAP2A, FOS, PANX1, NFIX and WNK1 were verified to play important roles in the pathogenesis of periodontitis-related T2D, shedding light on the discovery of potential drug targets for periodontitis patients to prevent T2D." (PMID 38811930, 2024).
pneumonia (1 paper, 2025). An acute, acute and chronic, or chronic inflammation focally or diffusely affecting the lung parenchyma, caused by an infection in one or both of the lungs (by bacteria, viruses, fungi, or mycoplasma.). "Moreover, the observed DC recruitment in pneumonia and to tuft cell denatonium stimulation was dependent on Trpm5 and Panx1 signaling and correlated with an increased tuft cell number." (PMID 39794305, 2025).
polycystic kidney disease (1 paper, 2025). A usually autosomal dominant and less frequently autosomal recessive genetic disorder characterized by the presence of numerous cysts in the kidneys leading to end-stage renal failure. "In particular, 12f was a more potent Panx1 blocker than the reference compound CBX (IC50 = 2.7 μM versus IC50 = 7.1 μM), and its profile was further investigated in a cell culture model of polycystic kidney disease." (PMID 40430343, 2025).
polymicrogyria (1 paper, 2023). A developmental brain abnormality characterized by an excessive amount of small convolutions on the surface of the brain and cognitive dysfunction. "We identified 3 individuals with candidate de novo missense variants in PANX1 and extensive polymicrogyria on MRI." (PMID 37486637, 2023). "In addition to detecting pathogenic variants in genes previously linked to polymicrogyria (eg, ADGRG1/GPR56, SCN3A, TUBB2B), we discovered 6 genes linked to polymicrogyria for the first time (QRICH1, TMEM161B, PANX1, KIF26A, SCN2A, and MAN2C1)." (PMID 37486637, 2023).
retinoblastoma (1 paper, 2022). A malignant tumor that originates in the nuclear layer of the retina. "Therefore, we aimed to analyze the expression of connexins 37, 40, 43 and 45 and pannexin 1 in the retina and choroid during human eye development and in the tumor tissue of retinoblastoma and uveal melanoma." (PMID 35682601, 2022).
Right ventricular hypertrophy (1 paper, 2021). In this case the right ventricle is more muscular than normal, causing a characteristic boot-shaped (coeur-en-sabot) appearance as seen on anterior- posterior chest x-rays. "The Fulton index, a ratio of right ventricular (RV) weight to left ventricle plus septal (LV + S) weight, was not altered in Panx1 cKO-EC mice compared to control mice, suggesting a lack of right ventricular hypertrophy in these mice." (PMID 34490843, 2021).
Shock (1 paper, 2022). The state in which profound and widespread reduction of effective tissue perfusion leads first to reversible, and then if prolonged, to irreversible cellular injury. "Together, these results suggest that PANX1 plays a vital role in LPS‐induced systemic endotoxic shock." (PMID 35593197, 2022).
Skeletal muscle atrophy (1 paper, 2024). The presence of skeletal muscular atrophy (which is also known as amyotrophy). "Nevertheless, the reduction in ATP in our models of skeletal muscle atrophy might also reflect an increase in pannexin-1, which forms ATP-permeable channels in the sarcolemma." (PMID 38892242, 2024).
spinal cord injury (1 paper, 2021). Penetrating and non-penetrating injuries to the spinal cord resulting from traumatic external forces (e.g., WOUNDS, GUNSHOT; WHIPLASH INJURIES; etc.). "Currently, the role of Pannexin-1, a homomeric membrane hemichannel on the neuron cell membrane, in the development of spinal cord injury (SCI) is largely unknown." (PMID 33986693, 2021).
steatosis (1 paper, 2024). Increased lipid within the cytoplasm of cells. "In livers of individuals and mice with steatosis, the expression of ATP-permeable channel PANX1 was increased (P < 0.01)." (PMID 38937853, 2024).
stomach adenocarcinoma (1 paper, 2021). "Therefore, we investigated the levels of PANX1 mRNA expression in various cancer types and found that PANX1 expression was significantly upregulated in many cancers, including ESCA, PAAD, and stomach adenocarcinoma (STAD)." (PMID 34796785, 2021).
temporal lobe epilepsy (1 paper, 2017). A localization-related (focal) form of epilepsy characterized by recurrent seizures that arise from foci within the temporal lobe, most commonly from its mesial aspect. "Meanwhile, the protein level of Panx1 has been found to be upregulated in surgically removed brain tissue of patients with temporal lobe epilepsy." (PMID 28036289, 2017).
thrombotic disease (1 paper, 2017). The formation of a blood clot in the lumen of a vessel or heart chamber; causes include coagulation disorders and vascular endothelial injury. "The role of Cxs and Panx1 in platelet aggregation is an exciting field of actual research, which holds promise for targeted drug development in order to prevent thrombotic diseases." (PMID 28420171, 2017).
tumor (66 papers, 2013 to 2026). "PANX1 localized to all regions within the cSCC tumour microenvironment, and increased levels were associated with larger tumour dimensions." (PMID 39560179, 2025). "Overall, this indicates PANX1 is increased in human cSCC tumours, where it localizes to all regions within the cSCC tumour microenvironment and is associated with a larger tumour size." (PMID 39560179, 2025). "The analysis of the effect of PANX1 expression on progression-free survival (PFS) subsequently also revealed that PANX1 was closely associated with tumor progression." (PMID 38254708, 2024). "High PANX1 expression was positively correlated with the recruitment of DCs and T cells within the tumor microenvironment and was associated with favorable survival outcomes in CRC patients who received adjuvant chemotherapy." (PMID 38195677, 2024). "Low tumor PANX1 expression or the loss-of-function P2RX7 allele leads to reduced infiltration of immune cells and poor survival outcomes after adjuvant chemotherapy treatment in CRC patients." (PMID 38195677, 2024). "Our study demonstrates that a Panx1 deletion cannot overcome the aggressive tumorigenic effect of Braf(V600E)/Pten(del) driver mutations, but it increases the tumor T‐cell infiltration with a preference in CD8+ cytotoxic T cells." (PMID 38327091, 2024). "In our study, the change in the expression pattern of Cx37, Cx40, pannexin-1, and vimentin was not only associated with different pathological stages (suggesting their possible role in tumor suppression), but also had a significant diagnostic/prognostic role." (PMID 36833374, 2023). "Ivermectin has recently been shown to have anti-tumor properties that we hereby link to its ability to augment P2X4/P2X7/Pannexin-1 signaling and caspase-1 activation, which is also associated with cancer cells’ elevated expression of P2X4/P2X7 receptors." (PMID 26552848, 2015). "From a therapeutic standpoint, Panx1 has been linked to the proinflammatory release of ATP from tumor cells treated with immunogenic cell death (ICD) inducing agents like anthracyclines and oxaliplatin." (PMID 24600404, 2014). "Based on the analysis of whole transcriptome sequencing data, the expression level of Panx1 was related to the immune infiltration, affecting the infiltration of neutrophils, tumor-associated fibroblasts, macrophages, myeloid-derived dendritic cells (MDSCs), and monocytes in PDAC." (PMID 40909173, 2025). "Notably, whole-transcriptome analyses identified Panx1 as a ferroptosis- associated genes whose dysregulation correlated with drug resistance, tumor immune infiltration, and tumor stemness in lung adenocarcinoma (LUAD)." (PMID 40909173, 2025). "Low PANX1 expression or loss of PANX7 function may increase the risk of tumor relapse by reducing the recruitment of T lymphocytes that are necessary for antitumor immunity." (PMID 38195677, 2024). "Moreover, high tumor expression PANX1 was markedly associated with favorable patient survival outcomes." (PMID 38195677, 2024). "Moreover, patients with lower tumor PANX1 expression or patients who carried the loss-of-function P2RX7 variant have less immune cell infiltration and poor survival outcomes after adjuvant chemotherapy treatment." (PMID 38195677, 2024). "Nonetheless, further research is warranted to determine whether global Panx1 deletion alone exerts sex‐specific changes in the spleen morphology and whether this causes an immune dysregulation that could impact the tumor response in mice." (PMID 38327091, 2024). "We hypothesize that the lower expression of Cx37, Cx40, and Panx-1 and the higher expression of vimentin may be associated with a more aggressive tumor phenotype, possibly by regulating growth and tumorigenic properties." (PMID 36833374, 2023). "Therefore, further prospective studies are needed to validate the prognostic value of PANX1 and investigate underlying molecular mechanisms in tumor immunity." (PMID 34796785, 2021).